ACE (angiotensin I converting enzyme)
Diseases named in the same sentence as ACE in open-access papers (continued):
Sharing a sentence is not in itself a finding about the gene and the disease.
Hyperkalemia (continued). "However, in late stages of DN with chronic renal failure or ESRD, hyperkalemia is more likely to develop when ACE inhibitors are prescribed." (PMID 20046751, 2008). "Heparin can lead to hyperkalemia on its own, but the risk is further increased when used in conjunction with medications that can predispose to hyperkalemia like angiotensin converting enzyme (ACE) inhibitors, nonsteroidal anti‐inflammatory drugs (NSAIDs), and trimethoprim." (PMID 38024642, 2023). "This is important as hyperkalemia may be a harbinger for adverse outcomes, can lead to discontinuation of medications with proven benefit such as angiotensin converting enzyme (ACE) inhibitors or angiotensinogen receptor blockers (ARB) and contributes to increased health care resources and cost." (PMID 34104453, 2021). "In the absence of anuria due to comorbidities or intercurrent events, hyperpotassemia in CKD is caused by the use of some drugs (alone or in association) such as potassium sparing (ACE inhibitors, anti-aldosteronic diuretics), but not by the simple assumption of vegetables and fruits." (PMID 31137545, 2019). "At the stage of the addition of MRA to therapy, a gradual up-titration of the MRA dose or a concomitant thoughtful reduction of the dose of ACE inhibitor or ARB could prevent the occurrence of hyperkalaemia, except in cases of severe impairment of kidney function." (PMID 26822790, 2016). "This suggests that ACE inhibitors or ARBs could be associated with the increased risk of hyperkalaemia; MRAs alone might not have caused this adverse effect." (PMID 26822790, 2016). "The risk of developing hyperkalemia is increased by the use of drugs that disrupt K+ balance such as K+ sparing diuretics and blockers of the renin-angiotensin-aldosterone system (RAAS) (e.g., angiotensin-converting enzyme [ACE] inhibitors, angiotensin receptor blockers, spironolactone)." (PMID 25531770, 2014). "However, we found that those with CKD were less likely to receive ACE inhibitors which may be a reflection of concern of drug-related adverse effects, such as hyperkalemia or a hemodynamically mediated decrease in eGFR." (PMID 21917174, 2011). "Antihypertensive drugs such as angiotensin-converting enzyme (ACE) inhibitors have been used for the treatment of DKD and DR; however, it is not well tolerated in some aged patients and may increase the risk of hyperkalemia when used in combination with angiotensin-receptor blockers (ARBs)." (PMID 38831391, 2024). "Coadministration of ACE inhibitors and ARBs was more common in patients with AKI, dehydration, hypotension, syncope, hyperkalemia, genitourinary infections, and Fournier gangrene." (PMID 36694178, 2023). "In our study, only four HF patients did not use an ACE inhibitor, three due to hypotension and one because of terminal renal failure and hyperkalemia." (PMID 29559923, 2018). "Of the remaining 40 patients, 10 were not taking an ACE inhibitor or angiotensin receptor blocker (patient compliance 5, hypotension 2, renal dysfunction 1, hyperkalemia 1, planning pregnancy 1)." (PMID 28716801, 2017). "In 2012, the National Healthcare Services professionals were advised to initiate combination of an ACE inhibitor and ARB only under specialist supervision in patients with renal disease, taking into account the potential for adverse effects such as hyperkalaemia." (PMID 23866091, 2013). "Our animal model and clinical data also suggest that the lack of an observed ACE inhibition protective effect could be because the drug was started well after KTx due to concerns of hyperkalemia, reduced renal perfusion, hypotension, and anemia." (PMID 40327402, 2025). "The incidence of hyperkalemia among patients prescribed ACE inhibitors or ARBs concomitantly with eplerenone was 1.1% and 0.8%, respectively, and that of patients without concomitant use of ACE inhibitors or ARBs was 0.6% and 0.5%, respectively." (PMID 27843645, 2016).
Hyperkalemia (continued). "For example, we could not control for clinical decisions such as withholding an ACE inhibitor in a patient with hyperkalemia." (PMID 21917174, 2011). "Thus, spironolactone seems to have no additional antiproteinuric effects over ACE inhibitor therapy in patients with IMN and nephrotic syndrome and carries the risk of significant hyperkalemia." (PMID 27713239, 2010). "Reduced ACE inhibitor use could reflect risks of postural hypotension, hyperkalemia in combination with non-steroidal anti-inflammatory arthritis medications, less stringent blood pressure targets for the elderly with functional impairments, or avoidance of cough side effects." (PMID 29684077, 2018). "In a meta-analysis, combined treatment with an ACE inhibitor plus ARB was found to be more effective than monotherapy with an ACE inhibitor / ARB alone for reducing daily proteinuria in IgA nephropathy, without an increased risk of hyperkalaemia, but no improvement in GFR was observed." (PMID 23866091, 2013). "However, the combination of ARBs with ACE inhibitors is not recommended, because there is less evidence of a benefit from this combination on cardiovascular disease or DN compared to monotherapy, in addition to the increased incidence of side effects such as hyperkalemia." (PMID 34307650, 2021).
atherosclerosis (128 papers, 2003 to 2026). A disease characterized by the build-up of fatty material and calcium deposition in the arterial wall resulting in partial or complete occlusion of the arterial lumen. "Several studies have reported associations between ACE gene polymorphisms (insertion/deletion) and cardiovascular diseases, including endothelial dysfunction, atherosclerosis, and heart failure." (PMID 35885904, 2022). "This suggests that the ACE/Ang-II/AT1R pathway can induce atherosclerosis, which would then account for the correlation between plasma ACE levels and the risk of ASCVD." (PMID 35885904, 2022). "Alternative treatments for the prevention of manifestations of cardiovascular diseases based on atherosclerosis in patients at risk include the use of ACE inhibitors, as well as, according to recent large meta-analyses, statin therapy." (PMID 35805936, 2022). "An association between the ACE I/D polymorphism and the extension of atherosclerosis was shown among men with high total cholesterol levels (>200 mg/dl), low HDL cholesterol levels (≤40 mg/dl) and high LDL cholesterol levels (>130 mg/dl)." (PMID 34834033, 2021). "Angiotensin production from endothelial cells is regulated by angiotensin-converting enzyme (ACE) which in turn exerts control over events like smooth muscle growth and proliferation during atherosclerosis also causing vascular wall injury." (PMID 33703990, 2021). "The present study seeks to examine the relationship between ACE I/D polymorphism with the risk of atherosclerosis." (PMID 31370787, 2019). "This study was planned to investigate the association between ACE I/D polymorphism and the risk of atherosclerosis, and the effect of genotypes on ACE activity." (PMID 31370787, 2019). "A variety of investigations have reported the impact of ACE I/D polymorphism in several cardiovascular diseases including endothelial dysfunction, atherosclerosis, and heart failure." (PMID 31370787, 2019). "According to Gensini score, ACE I/D polymorphismwas associated with progression and development of atherosclerosis in venousbypass grafts (P=0.02)." (PMID 26735603, 2015). "Genotype and allele frequencies of ACE I/D polymorphism in studiedpatients with vein graft atherosclerosis." (PMID 26735603, 2015). "Effect of ACE I/D polymorphism on progression of atherosclerosis in veingrafts of the studied patients." (PMID 26735603, 2015). "In the control healthy group and among the atherosclerosis related genes, subjects carrying ACE-Del allele were found 143 out of 171 (83.6%) while the β-fibrinogen (-455G>A) and HPA1 (b allele) were 43.9% and 33.9% of the population, respectively." (PMID 25973747, 2015). "In studies by Chen at al. the authors demonstrated that ACE deficiency in bone marrow–derived cells decreased hypercholesterolemia-induced atherosclerosis and correlated with reduced levels of MCP-1." (PMID 25003524, 2014). "There have been several reports on the association of the ACE gene polymorphism with atherosclerosis." (PMID 23826288, 2013). "We focused on those 48 probe sets, which were normalized toward B6 control level, to gain insight into mechanisms underlying the antioxidant-sensitive component of atherosclerosis treatment by the ACE inhibitor captopril." (PMID 23801967, 2013). "Microarray gene expression profiling showed that ACE-inhibition prevented the down regulation of all atherosclerosis-associated nerve-specific genes." (PMID 23801967, 2013). "The results we present demonstrate an association between the ACE c.2306-117_404 I/D polymorphism and the extension of atherosclerosis assessed by the Gensini score, with values ≥0." (PMID 22307319, 2012). "ACE is responsible for the conversion of angiotensin I to the peptide precursor angiotensin II, which has been implicated in the pathogenesis of atherosclerosis." (PMID 18637188, 2008).
atherosclerosis (continued). "ACE inhibitors have been shown to inhibit atherosclerosis in apoE-deficient mice and in several other animal models but failed in low-density lipoprotein (LDL) receptor– deficient mice despite effective inhibition of the reninangiotensin- aldosterone system." (PMID 12745671, 2003). "Similarly, the D allele in the ACE gene has been associated with an increased risk of atherosclerosis, especially in the European population, and a dose-dependent correlation has been observed." (PMID 39702436, 2024). "Atherosclerosis being a leading risk factor in developing SAC can be managed by administering statins to reduce cholesterol levels as well as angiotensin-converting enzyme (ACE) inhibitors in lowering blood pressure." (PMID 35464515, 2022). "This role of ACE and Ang II is mostly beneficial but may also cause vascular injury such as fibrosis and atherosclerosis when overactive." (PMID 36016727, 2022). "Recently, it has been shown that the ACE gene and smoking were related to plasma ACE levels and could potentiate the risk of atherosclerosis." (PMID 34834033, 2021). "This fact that the level of ACE activity and oxLDL were significantly higher in the patient group than the control group indicates the role of these two factors in increasing the risk of atherosclerosis." (PMID 31370787, 2019). "Since ACE expression on Mo2 cells is related to adverse outcome and enhanced cardiovascular disease in dialysis patients, these cells are thought to play a causal role in the progression of atherosclerosis." (PMID 27809785, 2016). "Furthermore, a potentially causal involvement of ACE upregulation for atherosclerosis initiation was studied." (PMID 25003524, 2014). "To investigate the role of ROS in atherosclerosis, we used ApoE-deficient mice, and compared the treatment effect of the antioxidant vitamin E with that of the angiotensin-converting enzyme (ACE) inhibitor, captopril, because angiotensin II is a major source of ROS in the vasculature." (PMID 23801967, 2013). "The chronic influence of higher levels of angiotensin II in the ACE D allele carriers, in comparison to the I allele carriers, may concur to the development and/or progression of atherosclerosis." (PMID 22307319, 2012). "Angiotensin-converting enzyme (ACE) is closely related to cardiometabolic risk factors and atherosclerosis." (PMID 38849492, 2024). "On the other hand, Ang II was found to participate in the development of insulin resistance and endothelial dysfunction in atherosclerosis, whereas the inhibition of ACE exerted positive effects in animal models of cardiometabolic syndrome." (PMID 38279313, 2024). "Inhibition of ACE and the RAAS by ACE inhibitors reduces blood pressure, enhances cardiac function, and decelerates the progression of atherosclerosis and kidney disease." (PMID 39046229, 2024). "ACE- or AT1R-deficient BM cells increased macrophage influx, aortic inflammation and atherosclerosis in a diet-induced model while ACE2-deficient-BM cells exacerbated the lesions." (PMID 36782016, 2023). "This study analyzes sex-based differences in renal structure and the response to the Angiotensin-Converting Enzyme (ACE) inhibitor enalapril in a mouse model of atherosclerosis." (PMID 37686247, 2023). "In this study, we represented two crucial aspects of ACE overexpression in myelomonocytic lineage cells under atherosclerosis conditions." (PMID 37928535, 2023). "Since peripheral blood circulating monocytes and splenic monocytes are precursors of atherosclerotic plaque-infiltrated macrophages, we investigated the influence of ACE overexpression in monocytes under atherosclerosis." (PMID 37928535, 2023). "The monocytes isolated from atherosclerotic ACE10/10 mice showed enhanced lipid metabolism, elevated mitochondrial activity, and increased adenosine triphosphate (ATP) levels which implies that ACE overexpression is already altered in atherosclerosis." (PMID 37928535, 2023).
atherosclerosis (continued). "This is a novel finding that ACE is a crucial factor in enhancing lipid metabolism not only for differentiated macrophages but also for peripheral blood circulating monocytes in atherosclerosis." (PMID 37928535, 2023). "We have already reported that ACE-overexpressed macrophages provided a protective function in atherosclerosis conditions by enhanced lipid metabolism represented by promoted β-oxidation and PPARα upregulation in the lesional macrophages." (PMID 37928535, 2023). "The authors also propose that bee pollen extract inhibits the development of atherosclerosis in the tested animals by reducing the activity of angiotensin-converting enzyme (ACE) and decreasing the level of angiotensin II." (PMID 35684067, 2022). "The adhesion of leukocytes and T-lymphocytes to the vascular epithelium, followed by the activation of endothelial ACE, initiates atherosclerosis." (PMID 35684315, 2022). "In preclinical studies, elevated plasma ACE activity was determined to accelerate the progression of atherosclerosis." (PMID 35885904, 2022). "The classical axis of RAS, i.e., angiotensin-converting enzyme (ACE)/Ang II/AT1 has been shown to contribute to the development of atherosclerosis and NAFLD." (PMID 34070749, 2021). "Experimental, epidemiological and clinical trials have shown that ACE inhibitors improve arterial endothelial function and hence slow down the progression of atherosclerosis." (PMID 34351937, 2021). "ACE inhibitors have proven to play an active role in the suppression of atherosclerosis, hence were incorporated in the drug discovery via pharmacophore modeling which was further screened against the ZINC database." (PMID 34351937, 2021). "An increased expression of Angiotensin II and ACE contributes to the relation of RAAS activation to atherosclerosis progression." (PMID 34206708, 2021). "Antihypertensive classes of drugs, angiotensin-converting enzyme (ACE) and bradykinin inhibitors, are currently widely used to reduce inflammation in several diseases, such as atherosclerosis, arthritis, steatohepatitis, colitis, pancreatitis and nephritis." (PMID 34084140, 2021). "It is known that anti-hypertensive drugs play an essential role in atherosclerosis, especially ACE inhibitors." (PMID 34351937, 2021). "Use of statins, angiotensin-converting enzyme (ACE) inhibitors, angiotensin receptor blockers (ARBs), β-blockers, and acetylsalicylic acid was also more common among patients with atherosclerosis compared to control subjects." (PMID 34300321, 2021). "Medication groups such as angiotensin-converting enzyme (ACE) inhibitors and statins are used in patients who have evidence of endothelial dysfunction and evidence of atherosclerosis." (PMID 33456670, 2020). "This study indicated that patients with atherosclerosis had higher levels of oxidized Low-Density Lipoprotein (oxLDL) and ACE activity (P < 0.05) as compared to controls." (PMID 31370787, 2019). "On the other hand, the atherosclerosis-decreasing potential of ACE-inhibition is reportedly independent from bradykinin and B2 bradykinin receptor stimulation." (PMID 30847343, 2019). "Increased level of the ACE and subsequent ACE activity by raising the production of angiotensin II can lead to atherosclerosis." (PMID 31370787, 2019). "In animal models ACE inhibitors and ARBs have been shown to reduce the progression of atherosclerosis, and in human study the perindopril has shown to prevent coronary remodeling." (PMID 30306089, 2018). "Among the atherosclerosis-related genes, ACE gene showed in the two studied populations the highest incidence of mutation." (PMID 25973747, 2015). "Among RAS blockers, the administration of ACE inhibitors to reduce the acute sequelae of atherosclerosis and transplant rejection has been shown in some excel studies." (PMID 26147666, 2015).